PAK1 (p21 (RAC1) activated kinase 1)
Diseases named in the same sentence as PAK1 in open-access papers (continued):
Sharing a sentence is not in itself a finding about the gene and the disease.
breast carcinoma (continued). "PAK1, a prototype of group I PAKs, was known to function in the key steps of human cancer progression; and its roles were well studied in multiple malignancies, including breast cancer, colon cancer, lung cancer, melanoma, prostate cancer, ovarian cancer and TSCC." (PMID 32190006, 2020). "Inhibition PAK1 could block the Akt/mTOR signaling pathway to benefit breast cancer therapy." (PMID 32863957, 2020). "Our results reveal that JAK2/PAK1 dysregulation inhibits the Stat3 signaling pathway and CSC formation, the PAK1/Stat3 complex regulates IL-6 gene expression, PAK1/Stat3 signaling regulates CSC formation, and PAK1 may be an important target for treating breast cancer." (PMID 31658701, 2019). "This study used both pharmacological and molecular approaches to investigate the hypothesis that the efficacy of free IPA‐3 and SSL‐IPA‐3 is dependent on the expression of PAK‐1 in diverse cancer cells, including prostate and breast cancer, as well as melanoma cells." (PMID 31516713, 2019). "Interestingly, the absence of PAK1 drastically affected the expression of the FA/BRCA genes in the breast cancer cell lines with amplification and/or overexpression of PAK1 and had little effect in breast cancer cells with low expression levels of this protein kinase." (PMID 27740936, 2016). "To determine whether PAK inhibition could promote cell death in these cells, we calculated the percentage of apoptotic cells in HCC1419, BT-474, MDA-MB-361 and SK-BR-3 breast cancer cells treated with vehicle, PF-3758309 or transfected with PAK1 targeting siRNAs and incubated with cisplatin." (PMID 27740936, 2016). "Finally, we showed that combined inhibition of PAK and PARP had a synergistic effect in PAK1 amplified or overexpressing breast cancer cells, were the dual inhibition of these molecules totally abrogated colony formation, enhanced apoptosis and impaired tumor growth in a xenograft setting." (PMID 27740936, 2016). "In order to assess whether PRL-induced tyrosyl phosphorylation of PAK1 has a physiological effect on breast cancer metastasis, TMX2-28 stably overexpressing GFP, myc-PAK1 WT, or myc-PAK1 Y3F were inoculated in mouse mammary fat pads and mice were treated with PRL for 8 weeks." (PMID 27542844, 2016). "Interestingly, the depletion or chemical inhibition of PAK in PAK1 amplified or overexpressing breast cancer cells treated with DNA damaging agents, compromised the ability of these cells to form Rad51 foci, induced cell cycle arrest, promoted apoptosis and resulted in reduced colony formation." (PMID 27740936, 2016). "While immunohistochemical staining of PAK1 in breast cancer patient specimens was correlated to tamoxifen resistance, possibly related to PAK1-mediated phosphorylation of ERα, PAK6 binds ERα and inhibits its transcriptional activity, and this PAK6-ERα interaction could be enhanced by tamoxifen." (PMID 26554417, 2015). "Moreover, Pak1 mediated phosphorylation of ERα at Ser305 has shown to enhance transactivation of ERα leading to up-regulation of ER-regulated genes, such as cyclin D1, which in turn promote hormone-independent growth of breast cancer cells." (PMID 26218748, 2015). "Given that PAK1 regulates the cytoskeleton and microtubule inhibitors are used as standard-of-care chemotherapy in advanced breast cancer, we explored the molecular and cellular mechanisms for this therapeutic combination and showed increased anti-tumor efficacy in breast cancer cells." (PMID 25902869, 2015). "Moreover, the phenotypic and morphogenic alterations resulted from K299R PAK1 expression included stabilization of focal adhesions and stress fibers as well as extensive cell spreading, thus reducing the motility and invasiveness of breast cancer cells." (PMID 25093037, 2014).
breast carcinoma (continued). "In addition to Pak4, other Pak family members are also overexpressed in breast cancer, particularly Pak1.14, 15, 16, 17, 18, 19, 20 Pak4 appears to be unique, however, in that wild-type Pak4 alone is sufficient to cause tumorigenesis in mice when overexpressed." (PMID 23732710, 2013). "It is interesting that the frequency of dysregulated expression of PAK1 was more frequent than would be predicted by genomic amplification alone and additional regulatory mechanisms that may increase PAK1 expression in breast cancer, such as via microRNA genes, remain to be fully explored." (PMID 21653999, 2011). "Consequently, the activation of PAK1 is essential for LPA-stimulated breast cancer cell migration." (PMID 21209852, 2010). "Thus, inactivation of Ebp1 may play a role in the ability of PAK1 to contribute to breast cancer progression and tamoxifen resistance." (PMID 18283314, 2008). "CRIPAK prevents PAK1-mediated LIMK activation and contributes to estrogen receptor (ER) transactivation in breast cancer cells." (PMID 40001545, 2025). "The log-rank P values were all less than 0.05, suggesting that patients with high expression of PAK1 and HDAC6/10 had higher mortality rates than those with low expression, indicating the potential of PAK1 and HDAC10 as therapeutic targets for breast cancer." (PMID 40302782, 2025). "In breast cancer BMX overexpression promotes proliferation by upregulating the activity of downstream substrates Protease Activated Receptor 1 (PAR1), p21 Activated kinase 1 (PAK1), and Signal Transducer and Activator of Transcription 1 (STAT1;)." (PMID 41213918, 2025). "In MDA-MB-231 human breast cancer cells, HGF stimulated the transportation of the PAK1/WAVE2 complex to the leading edge of lamellipodia through phosphorylation of STMN1S38." (PMID 40723207, 2025). "Combining PAK1 inhibitors with ET and CDK4/6 inhibitors represents a promising strategy to address resistance and improve patient outcomes in this aggressive breast cancer subtype." (PMID 40001545, 2025). "First, we examined the levels of PAK1, HDAC6, and HDAC10 in breast cancer tissues at different disease stages." (PMID 40302782, 2025). "To confirm PAK1 and HDAC IIb as potential therapeutic targets for breast cancer, we analyzed their expression levels and survival curves during different stages of tumor development." (PMID 40302782, 2025). "It is particularly interesting because we have previously shown that PRL-activated pTyr-PAK1 induces secretion of MMP-1 and MMP-3 in the breast cancer cells grown in 3D collagen IV." (PMID 38660565, 2024). "Based on our results, we propose Pak1 inhibitors combined with ET and CDK4/6 inhibitors as a possible approach for the treatment of ER+ resistant breast cancers." (PMID 37258566, 2023). "Rac1 signaling activates IQGAP1, P21-Activated Kinase 1 (PAK1), and filamin in invasive lymphoma and breast carcinoma cells, resulting in filamin cytoskeleton activation and metastasis." (PMID 38102637, 2023). "In conclusion, our data suggested a pivotal role for Pak1 in resistance to ET and CDK4/6i in ER+ breast cancers." (PMID 37258566, 2023). "P21-activated kinase 1 (PAK1) is known to be overexpressed in several human tumour types, including breast cancer (BC)." (PMID 37368917, 2023). "The highest proportion of cases with increased CN of PAK1 (≥4) was found in the HER2 type and Luminal B (HER2-) breast cancer subtype." (PMID 37368917, 2023). "Both PAK1 and PAK4 regulate the stemness of breast cancer stem cells, which leads to drug resistance." (PMID 36230657, 2022). "Previous findings on the relationship between PAK1 and NRG1 have been mainly reported in breast cancer cells and tumor cell lines." (PMID 35625715, 2022). "PAK1 phosphorylates ER-α and NRIF3 (co-activator of ER-α), thereby leading to the estrogen responsiveness of breast cancer cells." (PMID 36230657, 2022). "Stabilisation of ELF3 by PAK1 promoted ERK signalling and anchorage-independent growth in breast cancer cells." (PMID 34066106, 2021).
breast carcinoma (continued). "Another study revealed that inhibition of AURKA and PAK1 synergistically decreased survival of cancer cells and tumor growth in luminal and HER2-enriched breast cancer patient-derived xenograft mouse models." (PMID 33796531, 2021). "It is also reported that combined inhibition of PAK1 and PARP had a synergistic effect on suppressing cancer cell proliferation and tumor growth in PAK1 overexpressed breast cancer." (PMID 33796531, 2021). "In Luminal A breast cancers, the positive survival effects of AMPK, MARK3, PAK1, BRSK1, SNRK, and QSK are maintained in the pre-chemotherapy but not in the post-chemotherapy cohorts." (PMID 34084284, 2021). "In all breast cancer combined, high expression of LKB1, AMPK, LYK5, MARK1, MARK2, NUAK2, PAK1 (both probe sets), SIK1, SIK2, BRSK1, BRSK2, SNRK, and QSK was positively correlated with improved survival compared to low expression of these genes." (PMID 34084284, 2021). "In breast tumors, the down-regulation of ACE2 contributes to the invasion and metastasis of breast cancer cells through the store-operated calcium entry (SOCE) and PAK1/NF- κB/Snail1 pathways." (PMID 34369278, 2021). "In breast cancer and gliomas, HOXD10 downregulation results in the downregulation of miR-7 and upregulation of p21-activated kinase 1 expression (PAK1), which culminates in higher aggressiveness of these cancer types facilitating invasion and metastasis." (PMID 33375038, 2020). "Therefore, PAK1 and Aurora A dual-inhibition could benefit breast cancer treatment." (PMID 32863957, 2020). "More than 50% of human breast cancers display altered expression and activity of PAK-1, which correlated with increased survival of cancer cells, suggesting PAK-1 as a potential therapeutic target." (PMID 33321758, 2020). "This is, as far as we know, the first report of a direct correlation between PAK‐1 expression and efficacy of IPA‐3 in breast cancer." (PMID 31516713, 2019). "To examine the function of PAK1 in breast CSC formation, we cultured and isolated mammospheres derived from breast cancers." (PMID 31658701, 2019). "We investigated the antiproliferation effect of the PAK1 inhibitors IPA-3 and ivermectin on human breast cancers." (PMID 31658701, 2019). "As PAK1 is strongly expressed in squamous non-small cell lung cancer (NSCLC) cells, we assessed the protein level of PAK1 in breast cancer cells and CSCs by immunoblot analysis." (PMID 31658701, 2019). "To determine if these results were specific to MDA-MB-231 cells, we generated PAK1 knockdowns in the brain-metastatic cell line MDA-MB-231BR and the metastatic HER2 positive breast cancer cell line 21MT-1." (PMID 30651600, 2019). "We found that PAK1 interacts with JAK2 and Stat3, and then activates Stat3 signaling to support mammosphere formation and stemness of breast cancer cells." (PMID 31658701, 2019). "The serine-threonine kinases Aurora A (AURKA) and p21-activated kinase 1 (PAK1) are frequently overexpressed in breast tumors, with overexpression promoting aggressive breast cancer phenotypes and poor clinical outcomes." (PMID 31254157, 2019). "Overexpression of PAK1 has been correlated with NSCLC, breast cancer, prostate cancer, pancreatic cancer, gastric cancer, colorectal carcinoma, and oral cancers." (PMID 29596304, 2018). "HRG is known to induce Rac1 activation and subsequent phosphorylation of p21 (RAC1)-activated kinase 1 (PAK1), a critical effector protein of Rac1 signaling, in breast cancer cells." (PMID 29534468, 2018). "MiR-497 can downregulate the expression of PAK1 by directly and specifically targeting its 3’UTR in breast cancer cells." (PMID 29596304, 2018). "We then focused the comparison of CNAs on known driver oncogenes located within regions frequently amplified in breast cancer: ERBB2 (17q12), CCND1 (11q13.3), FGFR1 (8p11.23), MYC (8q24), and PAK1 (11q14.1)." (PMID 27028851, 2016).
breast carcinoma (continued). "Taken together, these data suggest that PRL-mediated pTyr-PAK1 is important in regulating the dynamic activation of FAK and subsequent breast cancer cell migration and invasion." (PMID 27542844, 2016). "This revealed several known kinase targets in breast cancer such as ERBB2, PAK1, RPS6KB1 and PTK2 (refs 16, 17), together with a new candidate kinase target, TLK2." (PMID 27694828, 2016). "We demonstrate here that tyrosyl phosphorylation of PAK1 in response to PRL regulates PTP-PEST-dependent FAK dephosphorylation, resulting in augmented breast cancer cell migration and invasion and proposed the mechanism explaining these findings." (PMID 27542844, 2016). "Because reduced PAK1 activity impaired FA/BRCA function, inhibition of this kinase in PAK1 amplified and/or overexpressing breast cancer cells represents a plausible strategy for expanding the utility of PARP inhibitors to FA/BRCA-proficient cancers." (PMID 27740936, 2016). "For example, the breast cancer cell line MDA-MB-175 has high miR-155 expression, PAK1 genomic amplification and PAK1 mRNA overexpression." (PMID 26121028, 2015). "Comparison of copy number analysis of HMEC, SUM149PT, SUM1315MO2 adherent cells revealed high copy numbers of AKT1, AURKA, CDK4, EGFR1, PAK1 and MYC in breast cancer cells as compared to HMEC cells." (PMID 26608463, 2015). "Conversely, ectopic expression of kinase dead K299R PAK1 suppressed JNK activity as well as the AP-1 promoter transcription activity, which is known to transcribe genes that involved in breast cancer invasiveness." (PMID 25093037, 2014). "Blocking Pak1 activity, in contrast, inhibits transformation of MCF10A cells by ErbB2 and blocks tumor formation in mice in response to ErbB2 positive breast cancer cell lines." (PMID 23326684, 2012). "miR-7 was also observed to reduce the expression of several oncogenes including PAK1 (p21 activated kinase 1) and IGF-1R (insulin-like growth factor 1 receptor) in breast cancer and tongue squamous cell carcinoma (TSCC) cell lines respectively." (PMID 22876288, 2012). "Taken together, we demonstrate for the first time a functional linkage between breast cancer cell motility and Rac1-ROS-PI3K/Akt-PAK1 signaling pathway, which sheds light on new therapeutic targets for breast cancer." (PMID 23554696, 2011). "A combination of PAK-1, phosho-PKA, a marker of activated PKA, and the phosphorylated S305 marker identified approximately 60–70% of all tamoxifen resistant cases in breast cancer." (PMID 22295213, 2011). "In summary, this study identifies a novel signaling pathway that accounts for EGF-induced breast cancer cell migration, including activation of Rac1, generation of ROS, subsequent activation of PI3K/Akt and PAK1." (PMID 23554696, 2011). "The PI3K/PAK1/ERK signaling pathway for LPA-stimulated breast cancer cell migration is identified and LPA is found to stimulate ROS generation in breast cancer cells." (PMID 21209852, 2010). "It has been proposed that Pak1 phosphorylates LC8 at serine 88 and that this event prevents BimL-dependent apoptosis in breast cancer by affecting LC8-BimL dimers." (PMID 19557173, 2009). "The LC8-Pak1 interaction has attracted significant interest as both Pak1 and LC8 appear to be coordinately upregulated in breast cancer specimens." (PMID 19557173, 2009). "P21-activated kinase 1 (PAK1), a member of the yeast sterile 20 (Ste20) family of protein kinases, is also regulated by HRG and involved in breast cancer progression." (PMID 18283314, 2008). "Thus, our current data on pTyr-PAK1 regulation of EMT bring insight into the role of PAK1 and PRL in human breast cancer." (PMID 38660565, 2024). "PAK1 is upregulated in various cancer types, integrates various signalling pathways, such as PI3K and RAS, and has been reported to phosphorylate and inactivate FOXO1 in breast cancer and FOXO6 in liver ageing." (PMID 39499086, 2024).
breast carcinoma (continued). "Additionally, we have demonstrated that pTyr-PAK1, in response to PRL, regulates PTP-PEST-dependent FAK dephosphorylation, resulting in augmented breast cancer cell migration and invasion." (PMID 38660565, 2024). "In conclusion, our evidence suggests that the aberrant activation of Pak1 might play a key role in resistance to endocrine therapy and CDK 4/6i in ER+ breast cancer cells." (PMID 37258566, 2023). "The phosphorylation of β-Catenin by PAK1 is required for the ErbB2-induced efficient transformation of mammary epithelial cells, while, PAK4 regulates the stability of p57(Kip2), thereby resulting in the proliferation of breast cancer cells." (PMID 36230657, 2022). "In the study of breast cancer cells without metastatic potential, the overexpression of continuously activated PAK1 promotes cell migration and proliferation." (PMID 34651424, 2021). "Given the importance of PAK1 and LIMK1 in breast cancer metastasis, we examined whether the PAK1/LIMK1/Cofilin1 signaling pathway is the downstream signaling cascade of SphK2/S1P." (PMID 33968977, 2021). "ChIP-PCR products were detected in breast cancer cells by using a Stat3 or PAK1 antibody, but not detected with the control IgG." (PMID 31658701, 2019). "Of relevance to breast cancer, both AURKA and PAK1 phosphorylate estrogen receptor alpha (ERα) (on serines S118 (PAK1) and S305 (PAK1 and AURKA)) supporting ligand-independent transcription of ERα-dependent genes promoting proliferation, invasion, and endocrine resistance." (PMID 31254157, 2019). "The data showed differential PAK‐1 expression across all cell lines, with PAK‐1 expression being higher in cell lines derived from noncancerous or earlier stage breast cancer." (PMID 31516713, 2019). "The immunofluorescence analysis with anti-PAK1 and anti-Stat3 in breast cancer cells with/without ivermectin treatment showed that colocalization of PAK1 and Stat3 in the nucleus was reduced by ivermectin treatment." (PMID 31658701, 2019). "The mechanisms mediating the increased sensitivity of prostate and breast cancer cells to SSL‐IPA‐3 during PAK‐1 inhibition are probably not drastically different than those mediating the toxicity of free IPA‐3." (PMID 31516713, 2019). "In breast cancer cells, endogenous levels of Rac1, PI3K and PAK1 were all stimulated following treatment with epidermal growth factor (EGF) leading to increased migration, however in cells expressing a PAK1 kinase dead mutant this migratory response to EGF was significantly diminished." (PMID 27845911, 2017). "The EMSY, PAK1, RSF1, and GAB2 genes are located within the 11q13/14 breast cancer amplicon." (PMID 28391240, 2017). "More importantly, we confirmed that the significant downregulation of miR-494 and upregulation of PAK1 in breast cancer tissues compared with paired non-tumor specimens in breast cancer TMA assay." (PMID 28055013, 2017). "In contrast, the inhibition or depletion of PAK1 had little effect on these cellular processes in PAK1-non-amplified breast cancer cells." (PMID 27740936, 2016). "The expression of two FA genes, FANCD2 and FANCI, was confirmed by qPCR and western blot in PAK1 depleted human breast cancer cells with or without PAK1 amplification and/or overexpression." (PMID 27740936, 2016). "Consistent with our previous results, we found that breast cancer cells with amplification or overexpression of PAK1 are highly sensitive to cisplatin-induced apoptosis after PAK1 inhibition or depletion, whereas PAK blockade has a very modest effect in HCC1419 breast cancer cells." (PMID 27740936, 2016). "Both PAK1 and the hormone/cytokine prolactin (PRL) have been implicated in breast cancer cell motility, however, the exact mechanisms guiding PRL/PAK1 signaling in breast cancer cells have not been fully elucidated." (PMID 27542844, 2016). "A subset of breast carcinomas without genomic amplification also display high mRNA and protein expression of PAK1." (PMID 25902869, 2015).